DPP4 (dipeptidyl peptidase 4)
Diseases named in the same sentence as DPP4 in open-access papers (continued):
Sharing a sentence is not in itself a finding about the gene and the disease.
liver fibrosis (continued). "Interestingly, previous studies demonstrate that DPP4 is only expressed in Ac-HSCs and suggest inhibition of DPP4 activity could reduce hepatic fibrosis through suppression of HSCs proliferation and collagen synthesis." (PMID 26491462, 2015). "These biomarkers are acetoacetyl-CoA synthetase (AACS), dipeptidyl-peptidase 4 (DPP4), d-dopachrome tautomerase (DDT), glutamine synthetase (GLUL), and glutathione S-transferase (GST); particularly, the plasma DPP4 and GST levels were highly associated with CCl4-induced liver fibrosis." (PMID 26491462, 2015). "In human, increased plasma DPP4 and FAP enzyme activities have been reported in patients with NAFLD, liver fibrosis and cirrhosis." (PMID 34771657, 2021). "Liver fibrosis of NASH is characterized by the excessive accumulation of extracellular matrix, as well as activated HSCs expressing DPP4 on its surface." (PMID 33173107, 2020). "Taken together, OA, a TGR5 agonist, appears to potentiate the inhibitory effects on liver fibrosis development mediated by ANA, a DPP-4 inhibitor, in diabetic rats." (PMID 31561561, 2019). "In mice, DPP4is decrease liver fibrosis; however, this was not recapitulated by genetically eliminating Dpp4 as Picrosirius red staining revealed a trend toward increased fibrosis, and expression of Col1a1 and Col3a1 was increased in Dpp4–/– mice." (PMID 36472923, 2023). "DPP4 and FAP have established roles in metabolism, fatty liver, liver fibrosis and cirrhosis." (PMID 34771657, 2021). "DPP-4 inhibitors may prevent carcinogenesis by suppressing liver fibrosis in NASH, since liver fibrosis is the strongest determinant of HCC32–34." (PMID 31969650, 2020). "Male diabetic rats received intraperitoneal injection of porcine serum (PS) to induce liver fibrosis, and they were orally administered the following agents: oleanolic acid (OA) as a TGR5 agonist, anagliptin (ANA) as a DPP-4 inhibitor, and a combination of both agents." (PMID 31561561, 2019). "The use of the sodium-glucose cotransporter-2 (SGLT2) inhibitors and incretin treatments, including oral inhibitors of dipeptidylpeptidase-4 (DPP-4) and injectable glucagon-like peptide-1 (GLP-1) receptor agonists, ameliorated diabetic conditions and reduced liver fibrosis and inflammation." (PMID 28352640, 2017). "Expression of the gene regulated on activation, T cell expressed, and secreted (RANTES; Ccl5), which is associated with severe liver fibrosis, was also significantly upregulated in HFHC-fed Dpp4–/– mice, whereas no changes in Mcp-1 (Ccl2) or Eotaxin (Ccl11) gene expression were noted." (PMID 36472923, 2023). "In addition, we saw increased DPP4 (CD26) on CD4+ T cells and NK cells, which concurs with our previous observation that DPP4 gene knockout mouse livers had fewer intrahepatic CD4+ T cells in a liver fibrosis model." (PMID 34771657, 2021). "Furthermore, in an experimental liver fibrosis model, a dipeptidyl peptidase-4 inhibitor (DPP4-I), sitagliptin, attenuated liver fibrosis development along with the suppression of hepatic transforming growth factor (TGF)-β1, total collagen, and TIMP-1 levels in a dose-dependent manner." (PMID 30769840, 2019). "However, recent randomized controlled trials suggested that DPP-4 inhibitor alone does not improve liver fibrosis in NAFLD patients." (PMID 31561561, 2019). "We have previously shown that DPP4, but not SGLT2, expressed by Ac-HSCs and sitagliptin (a DPP4-I) inhibits hepatic fibrosis via the suppression of Ac-HSCs in rats." (PMID 32245205, 2020).
rheumatoid arthritis (31 papers, 2007 to 2025). A chronic, systemic autoimmune disorder characterized by inflammation in the synovial membranes and articular surfaces. "The marker at CFA36:7,366,577 is nearest dipeptidyl peptidase 4 (DPP4), a membrane bound peptidase previously associated with rheumatoid arthritis and OA." (PMID 28614352, 2017). "Changes in the expression and/or the blood plasma concentration of DPP4 are associated with several diseases including rheumatoid arthritis and OA." (PMID 28614352, 2017). "Although no functional studies have yet explored the effect of this variant on DPP4 expression, a recent genome-wide association study (GWAS) in the Chinese Han population reported a link between rs12617656 and rheumatoid arthritis, further implicating it in immune-mediated diseases." (PMID 41373842, 2025). "Furthermore, a recent meta-analysis found that DPP4 inhibitor administration was associated with a decreased risk of rheumatoid arthritis." (PMID 38127960, 2024). "A prior study on rheumatoid arthritis (RA) patients demonstrated lower DPP-4 values in subjects with RA, along with a decrease in proinflammatory cytokines associated with increased DPP-4 expression." (PMID 39390508, 2024). "Serum DPP4 activity, more than sCD26 expression, was found to be impaired in rheumatoid arthritis patients compared to healthy controls." (PMID 39001488, 2024). "DPP4/CD26 levels are decreased in serum of patients diagnosed with the commonly systemic autoimmune diseases, such as rheumatoid arthritis and systemic lupus erythematosus, which occur along with sSS." (PMID 34220840, 2021). "In a similar cross-sectional case–control study with rheumatoid arthritis patients, we examined the levels of serum sCD26 and DPP4 activity in patients’ groups defined according to the therapies (conventional or biological) with anti-TNF, anti-CD20, anti-IL6R, or Ig-CTLA4." (PMID 39001488, 2024). "The relationship between DPP4 and rheumatoid arthritis was investigated in rat models of arthritis induced by type II collagen or alkyldiamine, and the induction of arthritis could be inhibited by using DPP4 inhibitors." (PMID 36172198, 2022). "DPP-4 inhibitors suppress cytokine production, inhibit monocyte infiltration to tissue niches, reduce the disease severity of rheumatoid arthritis in an animal model, suppress the inflammatory response in association with multiple sclerosis, and suppress the symptoms of inflammatory bowel disease." (PMID 33401457, 2021). "Due to their inhibitory effects on T cell activation and function, DPP-4 inhibitors (DPP-4i) have been successfully evaluated in vivo as immunosuppressive therapies using animal models of rheumatoid arthritis (RA), multiple sclerosis (MS), and transplantation." (PMID 31134095, 2019). "DPP-4 release into circulation seems to be decreased in some rheumatologic diseases, including rheumatoid arthritis (RA)." (PMID 25140306, 2014). "Moreover, loss of CD26/DPP4 expression might also be observed under physiological conditions or in non-malignant pathological conditions such as aging and rheumatoid arthritis." (PMID 34885056, 2021).
renal fibrosis (29 papers, 2011 to 2026). A final common manifestation of a wide variety of chronic kidney diseases characterized by glomerulosclerosis and tubulointerstitial fibrosis. "Our results demonstrate that inhibition of ACE protects renal fibrosis by suppressing DPP-4-associated mesenchymal transformations and elevating the gene expression of antifibrotic microRNAs in the kidneys of diabetic mice." (PMID 32085655, 2020). "The present study, therefore, is a significant addition to the exiting knowledge of RAAS inhibitors and its implications on DPP-4 level and associated microRNAs regulations in the renal fibrosis." (PMID 32085655, 2020). "DPP-4 inhibition in the diabetic kidney, was found to ameliorate renal fibrosis which is associated with higher level of AcSDKP in the diabetic mice." (PMID 32085655, 2020). "Of note, a recent report disclosed that a newly introduced antidiabetic drug, linagliptin, a dipeptidyl peptidase-4 (DPP-4) inhibitor, ameliorates renal fibrosis in diabetic mice via the restoration of miR-29 variants." (PMID 30642005, 2019). "We investigated the comparative effects of the RAAS inhibitors, such as angiotensin-converting enzyme inhibitors (ACEi) and angiotensin receptor blockers (ARB) on the DPP-4-associated mesenchymal activation in diabetic kidney and its implication in renal fibrosis." (PMID 32085655, 2020). "Interestingly, we found that the DPP4 is gradually increased in the diseased kidneys associated with the progression of IgA and renal fibrosis in the patients, where DPP4 is predominately expressed on the renal epithelial cells showing by the epithelial specific marker keratin." (PMID 40607249, 2025). "Our findings demonstrate that depletion of renal DPP4 effectively restores renal function and suppresses renal fibrosis following I/R or UUO injury compared to the control group." (PMID 40607249, 2025). "We demonstrated that kidney-specific deletion of DPP4 effectively suppresses renal fibrosis with UUO and I/R in vivo." (PMID 40607249, 2025). "To elucidate the clinical importance of DPP4 in renal fibrosis, we examine its expression on patients with IgA nephropathy (IgAN)." (PMID 40607249, 2025). "As RAS is well-documented for driving the development of renal fibrosis in IgAN18, we examined its potential role in DPP4 regulation on the human renal epithelial cell line HK-2 in vitro." (PMID 40607249, 2025). "Specifically, ACEIs mitigate renal fibrosis by attenuating dipeptidyl peptidase-4 (DPP-4) and transforming growth factor-beta (TGFβ) signaling pathways, a function not observed with ARBs." (PMID 39911847, 2025). "The DPP4 inhibitor Linagliptin reduced myofibroblast conversion and reduced progression of renal fibrosis." (PMID 37492439, 2023). "Collectively, these findings suggest that DPP-4 inhibition can reduce microcirculation lesion-induced renal fibrosis in a GLP-1-dependent manner." (PMID 29607314, 2018). "Along these lines, high activity of dipeptidyl peptidase-4 (DPP-4), a multifunctional cell surface aminopeptidase, was suggested to contribute to renal fibrosis in DN and its inhibition showed renoprotective effects in recent studies." (PMID 29123184, 2017). "Even though both fractions could improve renal function and alleviate renal fibrosis, only F2 was able to reverse the DPP-4 and GLP-1R levels as well as attenuate oxidative stress in the kidney." (PMID 39856844, 2025). "As the role of DPP4 in the Ang II mediated renal fibrosis is unknown, we examined the changes of fibrotic gene expression in the HK-2 cells with genetical and pharmaceutical inhibition of DPP4 in vitro." (PMID 40607249, 2025). "Furthermore, our research and other groups' findings have revealed the abundant expression of DPP4 on the proximal tubule epithelial cells; however, the role of DPP4 in renal fibrosis remains elusive." (PMID 40607249, 2025).
renal fibrosis (continued). "Thus, our study provides the direct evidence demonstrating that high-level, renal tubular-specific expression of DPP4 promotes renal fibrosis." (PMID 40607249, 2025). "Nevertheless, the roles of DPP4 in the development of renal fibrosis are still largely unexplored." (PMID 40607249, 2025). "Additionally, we found a dramatic up-regulation of DPP4 expression in the UUO-injured kidney in mice at both protein and mRNA levels associated with the expression of renal fibrosis markers fibronectin (Fn) and α smooth muscle actin (α-SMA) in vivo." (PMID 40607249, 2025). "Depending on the pathogenesis of DN, some potential drugs corresponding to DN have also been shown to have therapeutic effects on DN in recent years, such as empagliflozin, where Linagliptin -mediated inhibition of dipeptidyl peptidase 4 (DPP4) hinders EMT to ameliorate renal fibrosis in DN." (PMID 39830349, 2024). "Therefore, the linagliptin-induced decrease in DPP-4 expression alleviates renal fibrosis in the aging kidney." (PMID 32489704, 2020). "Targeting of DPP4 may represent a novel therapeutic strategy for renal fibrosis." (PMID 40607249, 2025). "However, due to the different mechanism and metabolism of each drug, it is unclear whether other DPP‐4 inhibitors can effectively inhibit the process of renal fibrosis." (PMID 35560773, 2022). "Our previous studies have demonstrated that linagliptin, an FDA-approved specific inhibitor of dipeptidyl peptidase-4 (DPP4), effectively inhibits renal fibrosis in diabetic mice." (PMID 40607249, 2025). "Unexpectedly, kidney-specific deletion of DPP4 effectively ameliorated UUO and ischemia/reperfusion (I/R)-driven renal fibrosis in vivo." (PMID 40607249, 2025). "In the kidneys, the interaction of CD26/DPP4 and integrin β1 facilitates renal fibrosis by enhancing TGFβ receptor-mediated endothelial–mesenchymal transition." (PMID 39684311, 2024). "Members of miR-29 family negatively regulate DPP-4, so we tried to find out functional significance in between TGFβRs and DPP-4 with respect to renal fibrosis." (PMID 32085655, 2020). "To further investigate the interaction between DPP-4–Integrin β1 and Angptl4, we analyzed microRNA array data from nondiabetic mice and diabetic mice with severe renal fibrosis." (PMID 39630889, 2024). "In a diabetic mouse model, ACEIs were observed to ameliorate renal fibrosis by attenuating DPP-4 and TGF-β signaling but were not demonstrated by ARBs." (PMID 36249783, 2022). "Although this study did not examine DPP-4 expression in a model of renal fibrosis, several previous studies reported changes in DPP-4 expression induced by fibrosis around the endothelium, as evidenced by renal histology." (PMID 32489704, 2020). "DPP-4 inhibition has been shown to suppress TGF-β and α-SMA expression in renal tubular epithelial cells by blocking NF-κB,5 and attenuation of NF-κB and TGF-β signaling through DPP-4 inhibition has also been reported to suppress renal fibrosis." (PMID 28118775, 2017). "In summary, DPP-4 inhibition suppressed renal fibrosis and inflammation in a nondiabetic model of progressive renal fibrosis in mice, suggesting a renoprotective role." (PMID 28118775, 2017). "Here, we observed that DPP4 is dominantly expressed on the renal epithelial cells in kidneys of CKD patients and experimental models' unilateral ureteral obstruction (UUO) and ischemia/reperfusion injury (I/R), which is positively correlated with the renal fibrosis and failure in clinics." (PMID 40607249, 2025). "Therefore, this study aims to elucidate the biological function of kidney-specific DPP4 in renal fibrosis in non-diabetic conditions." (PMID 40607249, 2025). "Furthermore, these DPP‐4 inhibitors can inhibit the phenotypic transformation of renal microvascular smooth muscle cells and inhibit EndMT by upregulating bone morphogenetic protein receptor 2 and downregulating TGF‐β1, thus reducing renal fibrosis." (PMID 35560773, 2022).
renal fibrosis (continued). "DPP4 inhibitors (such as linagliptin and DA-1229) suppressed TGF-β/Smad-mediated renal fibrosis and prevented podocyte damage without lowering the blood glucose in diabetic condition." (PMID 31905169, 2020). "We examined the therapeutic effects of DPP-4 inhibition in mice with unilateral ureteral obstruction (UUO), a nondiabetic model of progressive renal fibrosis." (PMID 28118775, 2017).
Sepsis (29 papers, 2013 to 2026). Sepsis is defined as life-threatening organ dysfunction caused by a dysregulated host response to infection. "A large retrospective cohort study found that GLP-1 RA treatment was associated with a significant reduction in the risk of severe sepsis as compared to dipeptidyl peptidase-4 inhibitor (DPP-4i)." (PMID 40863575, 2025). "There was a lower risk for sepsis- or infection-related mortality in the GLP-1 receptor agonist group vs the DPP-4 inhibitor group was (HR, 0.61; 95% CI, 0.40-0.91; P = .02)." (PMID 35254430, 2022). "In the context of weighing the pros and cons of DPP-4 inhibitor use given the effects of these drugs on immune function, our results show that they have an insignificant influence of sepsis risk." (PMID 26463557, 2015). "The effects of DPP-4 inhibitors and TZDs on sepsis were neutral, but a reduced risk of sepsis occurrence was observed only in recent/current TZD users." (PMID 26463557, 2015). "The results showed significantly higher expression of DPP4 in the control group (p < 0.05), and its expression trend was consistent with the dataset, suggesting that DPP4 has strong diagnostic potential for sepsis and can be effectively validated in clinical settings." (PMID 40124361, 2025). "A stronger association might be identified when the DPP4-activity on day 1 is measured in a larger and more diverse sepsis patient population." (PMID 32315321, 2020). "Indeed, sepsis induced decrease of phospholamban phosphorylation level was alleviated by DPP4 deficiency, and associated with the cardiac function preservation." (PMID 24416433, 2014). "For sepsis prognosis, five proteins were significantly up-regulated: selenium binding protein-1, heparan sulfate proteoglycan-2, alpha-1-B glycoprotein, haptoglobin, and lipocalin; two proteins were significantly down-regulated: lysosome-associated membrane proteins-1 and dipeptidyl peptidase-4." (PMID 23372690, 2013). "In an overview of GLP-1’s biological functions in sepsis and its emerging therapeutic potential, 27 studies were analyzed, focusing on the organ-protective effects of GLP-1, GLP-1RAs, and DPP-4 inhibitors in in vivo models of sepsis." (PMID 41357527, 2025). "Studies have shown that the DPP4 inhibitor alogliptin can improve survival rates in sepsis mouse models, providing indirect support for the drug predictions in this study." (PMID 40124361, 2025). "We further dissected the effect of DPP4 inhibition on vascular barrier integrity in mice using a model of polymicrobial sepsis inducing severe systemic inflammation." (PMID 40817204, 2025). "Of note, DPP4 inhibitor application reduced the concentrations of various pro-inflammatory mediators in murine blood 18 h after sepsis induction." (PMID 40817204, 2025). "The DPP-4 signaling cascade has recently been shown to play a role in the pathologic characteristics of sepsis, owing to a selective cross-talk within the DPP-4 and nuclear factor-kappa B (NF-κB) signal pathways." (PMID 40430475, 2025). "Studies have shown that alogliptin reduces leukocyte activation and oxidative stress levels by inhibiting DPP4 activity, significantly improving survival rates in sepsis mouse models." (PMID 40124361, 2025). "ROC curve analysis demonstrated AUC values >0.7 for TXN and DPP4 in both the training and validation sets, indicating their potential to effectively distinguish patients with sepsis." (PMID 40124361, 2025). "Application of the DPP4 inhibitor sitagliptin specifically restored the sepsis-induced downregulation of cilium organization and cell structure and downregulated pathways involved in endothelial responses to inflammation." (PMID 40817204, 2025). "Although this study has revealed the diagnostic value of DPP4 and TXN in sepsis and their correlation with immune infiltration through bioinformatics methods, the specific molecular mechanisms still require further experimental validation." (PMID 40124361, 2025).